IL9 (interleukin 9)
Diseases named in the same sentence as IL9 in open-access papers (continued):
Sharing a sentence is not in itself a finding about the gene and the disease.
lung carcinoma (continued). "Since we have shown IL-9 promotes tumor growth by upregulation of Arg1 expression in mouse models, we next wanted to investigate whether this paradigm was conserved in the development of human lung cancer." (PMID 35778404, 2022). "By looking into the mechanism we found that consistent with the presence of Th9 cells in the tumor of NSCLC patients, targeted deletion of IL-9 resulted in significant upregulation of IL-21, a cytokine produced by Th9 cells that may regulate anti-tumor effects of Th9 cells in lung cancer." (PMID 35514957, 2022). "Thus, blocking IL-9 signaling on lung macrophages, when macrophages are IL-9R+, could be a feasible therapeutic strategy for lung cancer and potentially other lung diseases." (PMID 35778404, 2022). "However, the identity of IL-9 responsive cells in lung cancer is unclear." (PMID 35778404, 2022). "Thus, strategies blocking IL-9 emerge as a new approach for clinical therapy of lung cancer." (PMID 35514957, 2022). "IL-9, a Th2 cell cytokine, has been reported as one of the cytokines which are downregulated by B7H4 in lung cancer." (PMID 36980202, 2023). "Thus, IL-9 signaling might impact the tumorigenic effects of TAMs in lung cancer patients." (PMID 35778404, 2022). "Therefore, we asked if targeting of IL-9 function might be therapeutically useful in lung cancer." (PMID 35514957, 2022). "Accordingly, inhibition of IL-9 or IL-17 cytokines by neutralizing antibodies decreased epithelial-mesenchymal transition (EMT) and slowed lung cancer progression and metastasis." (PMID 34026764, 2021). "In lung cancer, specific T‐lymphocyte subsets induce EMT in co‐culture experiments via IL9 and IL17 secretion and block of IL9/IL17 reduced EMT and metastasis." (PMID 34459003, 2021). "In vitro experiments showed that IL-9 and MPE supernatants increased the proliferation of lung cancer cells, while the addition of anti-IL-9 abrogated this effect." (PMID 32508847, 2020). "The viral-induced immunogenic cell death and IL-9 accumulation might work together to transform the immunosuppressive TME and elicit potent antitumor effects in colon and lung cancer models." (PMID 38473379, 2024). "For instance, in lung cancer, IL-9 does not directly increase cancer cell growth but modulates cell proliferation and inhibits apoptosis, thereby supporting tumor survival." (PMID 39334861, 2024). "Specifically, we found that the absence of IL-9 inhibits lung carcinoma growth and drives tumor rejection in two independent murine models of NSCLC." (PMID 35514957, 2022). "To better understand the role of GSK-3α and examine the critical genes affected by GSK-3α in lung cancer, we initially screened a subset of NF-κB target genes such as MYC, WT1, BIRC2, IL-9, HMOX1, and TERT, which were regulated by a pan-GSK-3 inhibitor AR-014418 in pancreatic cancer." (PMID 27049759, 2016). "However, in lung cancer, CD11c+ TAMs may exhibit pro-tumorigenic effects when influenced by CD4+ T cells via interleukin-9 (IL-9)/arginase 1 (Arg1) axis." (PMID 41341850, 2025). "Furthermore, IL-9–producing Th9 and Th17 cells have been reported to drive metastasis and epithelial–mesenchymal transition (EMT) in both human and murine lung cancer cells by upregulating MMP-3, MMP-13, and other genes involved in angiogenesis and cell adhesion." (PMID 41302515, 2025).
multiple sclerosis (16 papers, 2017 to 2025). A progressive autoimmune disorder affecting the central nervous system resulting in demyelination. "In a postmortem study of the brains of patients with multiple sclerosis, it was shown that IL-9 reduces the activation state and promotes the anti-inflammatory properties of macrophages." (PMID 40563933, 2025). "IL-9 is a cytokine that decreases and has a protective function against neurodegeneration in patients with the relapsing-remitting form of multiple sclerosis (RRMS)." (PMID 39000506, 2024). "In contrast, in the multiple sclerosis brain system, IL9 acted on macrophages to enhance the production of TGFβ, consequently inducing an anti-inflammatory response." (PMID 36968220, 2023). "IL-9 is expressed in the CSF of patients with multiple sclerosis (MS) and inversely correlated with disease severity." (PMID 37221406, 2023). "Previous studies have shown IL-9 affects microglia in multiple sclerosis, and IL-9R expression has been detected in human blood monocytes and alveolar macrophages." (PMID 35778404, 2022). "Interleukin 9 (IL-9), produced mainly by T helper 9 (Th9) cells, has been recognized as an important regulator in multiple sclerosis (MS) and its animal model, experimental autoimmune encephalomyelitis (EAE)." (PMID 33971906, 2021). "In another study on multiple sclerosis, IL-9 activated STAT1 and STAT5, which are known to inhibit Th17 polarization, and reduced IL-17 production." (PMID 29887863, 2018). "The authors suggest that this mechanism may contribute to the beneficial effects of IL-9 that are observed in multiple sclerosis." (PMID 40563933, 2025). "Therefore, in vitro functional data from patient samples are necessary to understanding the role of IL-9 in multiple sclerosis." (PMID 31035677, 2019). "Multiple Sclerosis (MS), which is a TH17 driven disease, neutralizing IL-9 or IL-9R knockout attenuates disease progression and severity in animal model of MS." (PMID 31035677, 2019). "The involvement of IL-9 in AD is still unexplored, even though a recent study on an experimental autoimmune encephalomyelitis (EAE) model of multiple sclerosis highlighted IL-9 as a critical neuroprotective molecule, capable of interfering with inflammatory synaptopathy." (PMID 40313591, 2025). "Thus, the role of IL-9 in multiple sclerosis is not clear from the outcome of studies in animal model." (PMID 31035677, 2019).
viral infection (16 papers, 2013 to 2024). "Finally, Campisciano detected an increase of the relative vaginal abundance of Prevotella timonensis in women infected with HPV, which showed a decreased concentration of the IL-15, IL-7, and IL-9 that they associated with the virus infection." (PMID 33488574, 2020). "Several studies have also described the association between Th9/IL9 and viral infections." (PMID 29937515, 2018). "In particular, a modulator role of IL-9 on antiviral immunity has been suggested in human viral infections, that is, an association of elevated IL-9 levels and severe acute respiratory syncytial virus infections and nonresponse to treatment in chronic hepatitis C has been described." (PMID 29967565, 2018). "Data on IL-9 functions during human viral infection is scarce, but studies have shown an association of elevated IL-9 levels and severe acute respiratory syncytial virus infections and non-response to treatment of chronic hepatitis C, suggesting a modulator role of antiviral immunity." (PMID 26702627, 2016). "This can be correlated with the increased levels of IL-4 and IL-9, found in the plasma of these patients and is generally unproductive in protecting against viral infections." (PMID 35572555, 2022). "Due to the dual natural of IL-9 in viral infection and cancers, further experiments were needed for elucidation of Th9 activity in chronic HBV-infected diseases, including CHB and HCC." (PMID 34177894, 2021). "The role of IL-9 in the modulation of both Th1 and Th2 T cell immunity as well as in the protection and/or pathogenesis of viral diseases needs further investigations." (PMID 29967565, 2018). "Recent studies suggest that IL-9 plays an important role during human viral infection such as in severe acute respiratory syncytial virus infections and in viral myocarditis." (PMID 29967565, 2018). "Another explanation is that IL9 inhibits Th1 immune responses, which leads to persistence of viral infection." (PMID 29937515, 2018). "Cytokines and chemokines that showed limited response in mice with any viral infection included Eotaxin, GM-CSF, IL-1α, M-CSF, IL-2, IL-3, IL-4, IL-5, IL-7, IL-9, IL-12p40, IL-13, IL-15, IL-17, MIP2, LIX, MIP1β, RANTES, IL-12p70, and VEGF (data not shown)." (PMID 23441208, 2013). "However, it was shown that IL-9 could modulate CD4+ responses in some viral infections, including respiratory syncytial virus infection and coxsackievirus B3-induced myocarditis." (PMID 37649897, 2023). "Interestingly, this effect of EPs 7630 treatment was also detected in non-infected cells, boosting the production of immune-regulating cytokines IL-9, IL-12, and IL-15, and potentially setting the course for a more balanced immune response towards virus infection in epithelial cells (IV.)." (PMID 34759825, 2021). "However, the role of IL-9 in viral infection and VMC remains controversial and uncertain." (PMID 27766098, 2016). "In this study, we infected Balb/c mice with Coxsackievirus B3 (CVB3), and found that IL-9 was enriched in the blood and hearts of VMC mice on days 5 and 7 after virus infection." (PMID 27766098, 2016). "The levels of MIP-1β, IL-1α, G-CSF, and IL-9 were affected neither by MHV-1 viral infection nor Apta-1 treatment." (PMID 38474386, 2024). "While IL‐9 levels were elevated with viral infection, they were not affected by any of the treatments." (PMID 28474501, 2017). "The role of IL-9 in viral infections was not clearly defined by the previous literature." (PMID 37649897, 2023).
lupus (15 papers, 2014 to 2025). "Elevated IL9 expression has been linked to production of autoantibodies in lupus-prone mice and in skin of CLE patients who progressed to SLE versus those who did not." (PMID 35721085, 2022). "In the kidneys of lupus mice, IL-9+ cells were heavily infiltrated, and a higher proportion of PNA+ germinal center (GC) cells was observed." (PMID 40771819, 2025). "The expressions of Th9 cells and IL-9 are increased in the mucosal tissues of ulcerative colitis (UC) patients and peripheral blood of systemic lupus erythematosus (SLE) patients and are related to the activity and severity of SLE." (PMID 38605942, 2024). "In vivo studies have demonstrated increased IL-9+ lymphocytes in the spleen and kidneys of lupus-prone mice and significant correlation with GC cells." (PMID 39456692, 2024). "In lupus murine models, an expansion of Th9 cells in the spleens of lupus-prone mice was demonstrated and also serum IL-9 levels were elevated, which were positively correlated to anti-dsDNA antibody titer." (PMID 28877244, 2017). "Similarly, systemic lupus erythematosus patients show elevated IL-9 and Th9 cells in circulation, although IL-9 neutralization in lupus-prone mice reduces autoantibody production and renal pathology, especially when combined with IL-17 blockade." (PMID 41030439, 2025). "A high expression of IL-9 was also observed in the kidneys and spleens of lupus-prone mice MRL/lpr." (PMID 31035677, 2019). "Furthermore, using MRL/lpr mice (an animal model of lupus), it has been demonstrated that Th9 cells and IL-9 levels expand in the spleen and kidney of these mice, and neutralizing IL-9 antibody lead to diminished anti-DNA titers and alleviation of LN." (PMID 29441231, 2018). "Th9 cells are recently defined subset of Th cells producing IL-9 and have been associated with immune responses against intestinal worms and immunopathology of various allergic and autoimmune disorders, viz. systemic sclerosis, systemic lupus erythematosus (SLE) and EAE." (PMID 29675022, 2018). "Patients with SLE and lupus nephritis who received a combination of prednisolone, azathioprine, and mycophenolate exhibited a lower urinary IL-9 expression compared to healthy control individuals." (PMID 40771819, 2025). "Treatment with neutralizing anti-IL-9 antibody in vivo decreased serum anti-dsDNA-antibody titers and alleviated lupus nephritis in MRL/lpr mice, which suggests that IL-9 is a potential therapeutic target for SLE." (PMID 32455141, 2020).
mastocytosis (15 papers, 2010 to 2023). A clonal myeloproliferative neoplasm characterized by the proliferation and accumulation of neoplastic mast cells in one or multiple organs or organ systems. "Allergic symptoms are reduced in IL-9-deficient mice, whereas intestinal mastocytosis, intestinal permeability, and intravascular leakage are observed in mice overexpressing IL-9, leading to a predisposition to oral antigen sensitization." (PMID 33333859, 2020). "Airway mastocytosis was reduced in MC-deficient KitW/W-v mice along with reduced levels of IgE, IL-2, IL-9 and TGF-β." (PMID 28090087, 2017). "Deficiency in IL-9 or IL-9R attenuates intestinal anaphylaxis, while transgenic expression of IL-9 in the intestine results in local mastocytosis and increased susceptibility to intestinal anaphylaxis." (PMID 22413008, 2012). "Although IL-9 has been implicated in the growth of normal MCs, little is known concerning pro-oncogenic molecules and conditions triggering differentiation and growth of MC to lead to the histopathological image of overt mastocytosis." (PMID 24520283, 2014). "Imatinib, a tyrosine kinase inhibitor that reduces IL-9-mediated lung mastocytosis, reduced mastocytosis and production of inflammatory cytokines in a CF mouse model." (PMID 32397175, 2020). "IL-9 transgenic mice exhibited rapid expulsion of the intestinal nematodes and local mastocytosis in epithelial layer of the gut, trachea and kidney." (PMID 31905768, 2019). "Our results consent with the established function for IL-9 in the recruitment of mast cells and promotion of mastocytosis in general." (PMID 24516385, 2014). "IL-9 is a cytokine with pleiotropic function that also contributes to mastocytosis and mast cell activation." (PMID 24516385, 2014). "Transgenic expression of IL-9 in the lung results in allergic inflammation while blockade of IL-9 decreases allergic inflammation, mastocytosis and airway remodeling as well as inflammation." (PMID 22413008, 2012). "Based on our mouse model, IL-9 is considered to play a potential role in the development of MC hyperplasia/mastocytosis." (PMID 21297223, 2010). "In a first step, we confirmed that neoplastic MC in IL-9 transgenic NPM-ALK-induced mastocytosis indeed expressed the NPM-ALK protein." (PMID 21297223, 2010). "In summary, several different morphologic and phenotypic properties of MC in IL-9/NPM-ALK+ mice are highly reminicent of mastocytosis." (PMID 21297223, 2010). "The observation that transplantation of NPM-ALK-transfected progenitors into IL-9 transgenic mice results in a neoplastic disease resembling mastocytosis, is a remarkable phenomenon, and best explained by the ‘multi-hit’ theory of cancer development." (PMID 21297223, 2010). "Similarly, the systemic expression of IL-9 in transgenic animals resulted in lymphomagenesis, expansion of B-1 lymphocytes, high levels of IgE, and mastocytosis." (PMID 31035677, 2019). "Mucosal mast cells profusely secrete IL-9 and are critical in driving mastocytosis." (PMID 31035677, 2019). "Because IL-3 and IL-9 induce mucosal mastocytosis, we examined whether the animals developed mucosal mastocytosis after treatment with IL-2 and IL-18." (PMID 29731751, 2018). "Taken together, our data indicated a crosstalk between IL-9 and mast cell in SARS-CoV-2 infection, which is consistent with the previous findings that IL-9 promotes mastocytosis and mast cell functions by enhancing their survival." (PMID 37429848, 2023). "Together, our data show that neoplastic MC express IL-9 rececptors, that IL-9 and NPM-ALK upregulate MC-production in vivo, and that both ‘hits’ act in concert to induce a mastocytosis-like disease in mice." (PMID 21297223, 2010). "Forced increase in systemic IL-9 concentration by injection of a IL-9 transgenic (tg) cell line accelerated expulsion of Trichuris muris in C57BL/6 mice and IL-9 tg FVB mice displayed faster clearance of T. muris infection in the context of increased mastocytosis." (PMID 24516385, 2014).
mastocytosis (continued). "However, these IL-9-triggered accumulations of MC did by far not reach criteria for a primary MC disease (MC neoplasm=mastocytosis) in any of the animals examined." (PMID 21297223, 2010). "In summary, our data show that IL-9 and NPM-ALK cooperate in producing a mastocytosis-like disease in mice that resembles a primary MC disease in several different aspects, and may thus be a useful model for studying the development and pathogensis of mastocytosis." (PMID 21297223, 2010). "However, under the experimental conditions applied, neither IL-9 nor NPM-ALK alone (as single “hit”) were found to lead to the histopathological picture of mastocytosis (focal MC accumulations resembling SM) in any animal and organ examined (BM, spleen, liver, lung, thymus, gastrointestinal tract)." (PMID 21297223, 2010). "Transplantation of NPM-ALK-transduced progenitors into normal mice or maintenance of IL-9 transgenic mice without NPM-ALK both resulted in MC hyperplasia, but not in mastocytosis." (PMID 24520283, 2014). "Transplantation of NPM-ALK-transduced progenitors into normal mice or maintaintence of IL-9-transgenic mice without NPM-ALK each resulted in MC hyperplasia, but not in mastocytosis." (PMID 21297223, 2010). "However, human neoplastic MC in SM did not express ALK, and similar to IL-9, NPM-ALK alone led to MC hyperplasia only, but did not lead to the clinical picture of overt mastocytosis." (PMID 21297223, 2010).